POM121B (POM121 transmembrane nucleoporin B (pseudogene))
Description:
Putative component of the nuclear pore complex (NPC). The repeat-containing domain may be involved in anchoring components of the pore complex to the pore membrane (By similarity).
Gene: Unprocessed pseudogene on chromosome 7 (73,293,497 to 73,301,161, forward strand). Ensembl gene ENSG00000205578.
Subcellular location: Nucleus, nuclear pore complex